IL6 (interleukin 6)
Diseases named in the same sentence as IL6 in open-access papers (continued):
Sharing a sentence is not in itself a finding about the gene and the disease.
Obesity (continued). "Elevated IL-6 and CRP levels are common in obesity, and although direct evidence linking GCKR variants to obesity is limited, this pathway warrants further investigation." (PMID 41150798, 2025). "This AMPK activation has been shown to negatively regulate pro-inflammatory cytokines, including TNF-α, IL-6, and MCP-1, which are key mediators of chronic inflammation associated with obesity." (PMID 40733199, 2025). "Reductions in markers of systemic inflammation hsCRP (in both trials, 26–42%) and IL-6 (in the obesity trial, 4–13%) were also observed with orforglipron." (PMID 40481478, 2025). "Conversely, as an adipokine, IL-6 is chronically elevated in obesity and NDH, contributing to low-grade systemic inflammation and insulin resistance." (PMID 41187617, 2025). "Pro-inflammatory cytokines (such as TNF-a and IL-6) derived from chronic low-grade inflammation in obesity can activate the coagulation system, leading to the release of clotting factors, which are intricately linked with tumour growth and progression." (PMID 40558305, 2025). "During the early stages of NAFLD, obesity regulates fatty acid synthesis via the IL6/AKT/SREBP1c pathway." (PMID 39928768, 2025). "Ablating Stat3 in T cells reduces inflammation/obesity-induced insulin resistance, which is in part contributed to by the recruitment of IL-6-producing ATMs in obese mice." (PMID 40801626, 2025). "Paprika pigments have been reported to reduce the expression of obesity-related inflammatory markers, including interleukin-6 (IL-6), tumor necrosis factor-α (TNF-α), monocyte chemotactic protein-1 (MCP-1), and resistin in 3T3-L1 adipocytes." (PMID 39858523, 2025). "Obesity causes dysfunctional PVAT that leads to decreased adiponectin levels and increased leptin and IL-6 levels and contributes to atherosclerosis progression." (PMID 40137085, 2025). "The results of logistic regression analysis showed that obesity alone and type 2 diabetes with obesity were significantly associated with serum levels of TNF-α, IL-6, leptin, adiponectin, resistin, and ALR after adjusting for sex or age." (PMID 40095937, 2025). "Obesity-related excess adipose tissue releases pro-inflammatory cytokines, such as interleukin-6 (IL-6) and tumor necrosis factor-alpha (TNF-α)." (PMID 40565268, 2025). "For ChAdOx1‐S recipients, the demographic factors with the greatest influence on the variability in cytokine responses included chronic respiratory disease and cardiovascular disease, with IL‐12p70 and IL‐6 the largest contributors, as well as sex and obesity." (PMID 39872402, 2025). "For instance, C57BL/6 mice subjected to high-fat diets exhibit obesity and demonstrate increased levels of pro-inflammatory cytokines like TNF-α and interleukin-6 (IL-6), which are associated with liver inflammation and damage." (PMID 41001122, 2025). "Obesity often leads to a chronic low-grade inflammatory state, marked by elevated levels of pro-inflammatory cytokines such as interleukin-6 (IL-6) and high-sensitivity C-reactive protein (Hs-CRP)." (PMID 40641901, 2025). "In the current study, children with obesity/overweight and children with comorbid obesity/overweight and asthma showed higher IL-6 than children with asthma, which illustrates that IL-6 is involved in the pathogenesis of asthma in obese children." (PMID 40083433, 2025). "The effect of obesity on IL-6 level was previously shown to vary with age and sex; in this study, the effect of both variants was corrected for by the study design." (PMID 40003433, 2025). "For further characterization, we analyzed the expression of three marker genes for obesity, the pro-inflammatory cytokine Il6 and the adipokines Lep and AdipoQ, using RNAseq datasets of visceral AT and visceral adipocytes from lean and obese mice." (PMID 40498013, 2025). "Elevated IL-6 levels in obesity contribute to a chronic low-grade inflammatory state that supports tumor development and progression." (PMID 41007818, 2025).
Obesity (continued). "The authors of a 2024 meta-analysis of 44 randomised controlled trials concluded that, compared to other diets, the KD lowers levels of inflammatory markers, such as TNF-α (WMD: −0.32 pg/mL) and IL-6 (WMD: −0.27 pg/mL) (which are associated with obesity)." (PMID 40289934, 2025). "Beyond cellular differentiation, obesity is also characterized as a state of chronic low-grade inflammation, marked by elevated levels of adipokines and pro-inflammatory cytokines such as interleukin-6 and receptor activator of nuclear factor-kappa B ligand." (PMID 40070589, 2025). "Increased levels of TNF-α and IL-6 in obesity contribute to systemic inflammation, insulin resistance, and the progression of metabolic syndrome." (PMID 40710568, 2025). "These systemic effects from obesity-related increase of IL-6 trans-signaling are also thought to play a role in chronic neuroinflammation and the progression of AD." (PMID 41277875, 2025). "Elevated levels of pro-inflammatory cytokines, such as TNFα and IL-6, which are commonly observed in obesity, can promote osteoclastogenesis through an NFκB-mediated pathway." (PMID 40260279, 2025). "In cases of obesity, adipose tissue releases pro-inflammatory cytokines such as TNF-α, IL-6, and CRP, which play a role in causing liver inflammation and injury." (PMID 41007669, 2025). "In conclusion, there were significant differences in IL-6, IL-10, IL-13, 25-(OH) D3 levels, and leptin levels among children with asthma combined with obesity/overweight and those with asthma or obesity/overweight alone." (PMID 40083433, 2025). "Obesity induces chronic inflammation primarily through the secretion of pro-inflammatory cytokines, such as IL-6 and TNF-α, and the accumulation of macrophages in adipose tissue." (PMID 40871683, 2025). "The inverse association observed in this study contrasts with the well-documented elevation of systemic IL6 levels in obesity, driven by chronic low-grade adipose tissue inflammation." (PMID 41150772, 2025). "A previous study found that the obesity-related proinflammatory cytokine IL-6 was related to asthma severity when metabolic syndrome co-occurred." (PMID 40083433, 2025). "In the setting of obesity, dysfunctional adipose tissue triggers the release of pro-inflammatory cytokines, including interleukin-6, tumor necrosis factor-α, and C-reactive protein." (PMID 41415798, 2025). "In the state of obesity, adipose tissue, particularly visceral fat, has been shown to release pro-inflammatory cytokines, such as IL-6 and TNF-α, which can lead to the activation of a systemic, chronic, low-grade inflammatory response." (PMID 40735221, 2025). "IL6, a central immunomodulatory cytokine, was unexpectedly elevated in normal-weight individuals compared to those with obesity." (PMID 41150772, 2025). "Semen samples from 272 male donors confirmed a correlation between obesity, sperm quality, and pro-inflammatory cytokine levels, showing elevated IL-6 and TNF-α in the semen of obese men, along with reduced sperm concentration and motility." (PMID 40564033, 2025). "Adipose tissue in individuals with obesity secretes pro-inflammatory adipokines and cytokines, such as leptin, IL-1β, and IL-6." (PMID 40218960, 2025). "Gal‐3 is positively correlated with obesity and inflammation, as measured by inflammatory markers IL‐6 and CRP." (PMID 41404534, 2025). "IL-6 and TNF-α are cornerstone pro-inflammatory cytokines that are elevated in obesity and autoimmune diseases and are directly implicated in prostate cancer pathogenesis." (PMID 41555998, 2025). "A three-week hypocaloric study in individuals with obesity found that a low-protein diet (10% of total energy) led to a more pronounced reduction in IL-6 compared with a high-protein diet (30% of total energy), despite similar energy restriction." (PMID 41190148, 2025).
Obesity (continued). "TNF-α and IL-6 are known to possess inflammatory properties and can induce insulin resistance, serving as significant links between obesity, diabetes, and chronic inflammation." (PMID 40225013, 2025). "In obesity, hypertrophic adipocytes release a spectrum of pro-inflammatory adipokines (e.g., leptin and resistin) and cytokines (e.g., IL-1β and IL-6), which are known to exacerbate autoimmune conditions." (PMID 40900762, 2025). "Factors such as age, race, gender, obesity, diabetes, hypertension, cardiovascular disease, low eGFR, high IL-6 levels, mechanical ventilation, and vasoactive drugs have been identified as independent predictors of AKI14,15." (PMID 39792860, 2025). "This includes: the inflammatory marker IL-6, Ca2+ ions, total protein content, and cortisol, all of which have been reported to be elevated in individuals with obesity." (PMID 41584074, 2025). "Low-grade systemic inflammation, characterized by elevated cytokines such as interleukin-6, has been observed in adolescents with obesity and correlated with abdominal pain." (PMID 41374033, 2025). "In white adipose tissue, expansion associated with obesity results in the secretion of adipokine such as TNF-α and IL-6, which recruit and activate macrophages, perpetuating inflammation." (PMID 41415265, 2025). "Moreover, COPD and obesity are associated with chronic airway inflammation and impaired interferon-mediated immunity, which may amplify cytokine production (notably IL-6, TNF-α, and IL-8), worsening pulmonary injury and contributing to acute respiratory distress." (PMID 41488075, 2025). "Obesity acts as a critical mediator in this process: Visceral adipose tissue secretes free fatty acids and pro-inflammatory cytokines (such as IL-6 and TNF-α), which not only exacerbate hepatic IR but also impair renal urate excretion." (PMID 41356818, 2025). "Chronic low-grade inflammation (CLGI), characterized by the persistent elevation of pro-inflammatory mediators such as CRP, IL-6, and TNF-α, is a defining feature of obesity-associated PCOS." (PMID 41239503, 2025). "IL-6 levels were significantly reduced in individuals with obesity with longer treatment durations and when synbiotics were used as an intervention." (PMID 41022286, 2025). "In contrast, IL-6 and cortisol concentrations were significantly higher in individuals with obesity, each showing medium-to-large effect sizes (r = 0.6 and r = 0.5, respectively)." (PMID 41584074, 2025). "The metabolic effects of IL6 have been found in IL6-KO mice, which exhibit mature obesity, insulin resistance, and hepatic inflammation." (PMID 40868889, 2025). "The necessity of conducting medical imaging and biomarker (e.g., adiponectin, IL-6, etc.)related studies to explore the pathological pathways of obesity-related inflammation and esophageal mucosal injury has been proven in practice." (PMID 41384250, 2025). "Under basal conditions in obesity, IL-6 is primarily derived from adipose tissue, where it contributes to a chronic pro-inflammatory state linked to impaired insulin signaling." (PMID 41002965, 2025). "CAFs secrete IL‐6 under oxidative conditions, mirroring adipocyte‐derived proinflammatory cytokines in obesity." (PMID 40599237, 2025). "Obesity is accompanied by elevated levels of pro-inflammatory cytokines such as TNF-α and IL-6, both of which are closely associated with insulin resistance and metabolic disorders, as well as diminished immune cell activity." (PMID 41460779, 2025). "The concomitant presence of COPD and obesity has also been correlated with increased levels of IL-6, CRP, and TNF-α." (PMID 40283443, 2025). "Circulating IL-6 levels are chronically elevated in people with obesity and T2D but are still much lower than that in people with cancer and muscular dystrophy." (PMID 40171198, 2025).
Obesity (continued). "Apart from acute stages of inflammation resulting e.g. from infections, elevated levels of CRP and IL-6 are also observed in a condition coined as low-grade inflammation such as obesity." (PMID 39899498, 2025). "Under pathological conditions, such as obesity and cancer, the level of IL6 secreted by adipocytes significantly increases." (PMID 40841364, 2025). "Interleukins such as IL-6 and IL-15 represent important modulators of local interactions between skeletal muscle and adipose tissue in obesity and T2DM." (PMID 41002965, 2025). "For example, adipokines such as leptin and adiponectin regulate energy homeostasis and lipid metabolism, while inflammatory markers like TNF‐α and IL‐6 highlight the role of chronic inflammation in obesity." (PMID 40551726, 2025). "Driving neuroinflammation involves blood-brain barrier (BBB) dysregulation and elevated levels of pro-inflammatory cytokines, such as TNF-α and IL-6, which are excessively released during obesity." (PMID 40277905, 2025). "In cancer, obesity-induced expression of growth factors, inflammatory cytokines (e.g., IL-6 and TNF-α), and adipokines (e.g., leptin) can induce dysregulation PI3K/AKT/mTOR signaling pathway, to induce cancer progression and predict a poor prognosis." (PMID 40863244, 2025). "Biomarkers such as leptin, adiponectin, and certain inflammatory cytokines (e.g., IL‐6 and TNF‐α) have shown promise in predicting the risk of obesity and its associated complications." (PMID 40551726, 2025). "Elevated levels of pro-inflammatory cytokines, including tumor necrosis factor-α (TNF-α) and interleukin-6 (IL-6), were observed in Zn-overloaded states, further exacerbating obesity-related complications." (PMID 41459237, 2025). "Obesity-induced visceral fat accumulation also leads to the secretion of pro-inflammatory cytokines, such as IL-6, which activate chronic systemic inflammation." (PMID 40852190, 2025). "In fact, obesity can impact serum concentrations of pro-inflammatory mediators [such as IL-6, CRP, TNF-α, resistin, and leptin] and anti-inflammatory mediators (Adiponectin and IL-10) in individuals with periodontitis." (PMID 40422620, 2025). "The term adipokine also encompasses molecules that are canonical players within the immune system, including cytokines like interleukin (IL)‐6 and tumour necrosis factor alpha (TNFα), which are elevated during obesity, and contribute to inflammation." (PMID 39428707, 2025). "This study aims to explore the combined role of ANGPTL3, 4, 8, omentin-1, leptin, TNF-α, and IL-6 molecules known for their roles in fat metabolism, obesity, and inflammation, yet whose connection to PCOS is still debated in the development of PCOS." (PMID 41341944, 2025). "Obesity represents an important risk factor for NODAT, which is explained by the involvement of adipose tissue in IL-6 synthesis, leading to increased insulin resistance." (PMID 41155647, 2025). "IL6 JAK-STAT signaling has been reported to impair the insulin-degrading enzyme, a protein found to be associated with obesity and T2D45." (PMID 39670387, 2025). "Obesity also drives infiltration of macrophages into periprostatic adipose tissue, where they secrete IL-6." (PMID 41139205, 2025). "Nevertheless, obesity was linked to heightened inflammatory responses in the GCF, marked by elevated concentrations of IL-6, TNF-α, and IL-1β." (PMID 40422620, 2025). "In obesity, pro-inflammatory adipocytes-derived cytokines (IL-6, TNF-α, and IL-1β) and C-reactive protein (CRP) are often elevated." (PMID 41375608, 2025). "In our study, significantly higher IL-6 expression was observed in colorectal cancer (CRC) patients with obesity (BMI ≥ 30 kg/m2) and increased waist circumference." (PMID 41007818, 2025). "Monocytes from people with obesity or primed with palmitate, a central component of circulating FFAs, presented elevated viral load and higher gene expression of IL‐6." (PMID 40265287, 2025).
Obesity (continued). "Among these immune cells infiltrating AT, macrophages are the most abundant and serve as key mediators of obesity-induced inflammation through the secretion of pro-inflammatory cytokines, such as interleukin-6 (IL-6) and tumor necrosis factor- α (TNF-α)." (PMID 41432903, 2025). "Obesity is a primary driver of elevated CRP due to adipose-derived pro-inflammatory cytokines like IL-6." (PMID 40566547, 2025). "Metabolic changes like obesity can increase IL-6 levels and promote immune tolerance, revealing a complex link between inflammation and metabolism." (PMID 40458085, 2025). "In obesity, IL-6 is released from visceral adipocytes into the portal vein and directly acts on the liver to induce the production of CRP." (PMID 40568560, 2025). "On the other hand, in an extensive systematic review and metanalysis of RCT studying the effect of dietary weight loss intervention on IL-6 and TNF-α in adults with obesity, only IL-6 was reported to be significantly reduced after at least 5% of weight loss." (PMID 40430061, 2025). "Obesity is known to impair leukocyte functionality; for example, monocytes from pregravid obese individuals release less IL6 upon LPS stimulation than those from normal-weight subjects." (PMID 41150772, 2025). "The controversial role of IL-6 in adipose tissue on obesity-induced dysregulation of glucose metabolism was reviewed recently by Wueest and Konrad." (PMID 40076884, 2025). "Interleukin‐6 (IL‐6), a major driver for secondary inflammation in obesity and diabetes, was increased in stimulated macrophages after SP exposure as opposed to vehicle‐treated or unstimulated macrophages." (PMID 41051359, 2025). "Studies have shown that DAV supplementation can reduce the levels of pro-inflammatory cytokines such as TNF-α, IL-1, and IL-6, which are involved in the pathogenesis of various chronic diseases, including obesity." (PMID 39974837, 2025). "In this context, specific pro-inflammatory cytokines such as TNF-α, IL-1β, and IL-6 have emerged as key players in the pathophysiology of obesity and its complications." (PMID 41141350, 2025). "The production of IL-6 escalates with increasing body fat and the presence of IR, while elevated TNF α levels are associated with two key components of MetS: obesity and IR." (PMID 40310144, 2025). "Pregnancy is associated with a metainflammatory state that is heightened by obesity, with primary increases in circulating interleukin 6 (IL-6) and C-reactive protein (CRP)." (PMID 40637163, 2025). "Obesity promotes a pro-inflammatory environment by elevating the levels of inflammatory mediators such as IL-6 (interleukin) and tumor necrosis factor alpha (TNF-α), while decreasing adiponectin, a molecule that has anti-inflammatory properties." (PMID 40943267, 2025). "For instance, pro-inflammatory cytokines like interleukin-6 (IL-6) and tumor necrosis factor-alpha (TNF-α) are elevated in obesity and have been associated with insulin resistance and beta-cell dysfunction." (PMID 40804870, 2025). "Mechanistically, obesity is characterised by chronic low‐grade inflammation that drives hepcidin synthesis via interleukin‐6 (IL‐6) signalling, thereby restricting iron absorption and mobilisation from macrophage stores." (PMID 40968580, 2025). "These associations were statistically mediated by IL-6 (12 % (p-valueFDR = 0.012) of the association with CVD, 17 % T2DM (p-valueFDR<0.001), 18 % hypertension (p-valueFDR<0.001), and 29 % obesity (p-valueFDR = 0.005))." (PMID 41019535, 2025). "Obesity not only exacerbates insulin resistance, but also produces reactive oxygen species (ROS) and a variety of inflammatory factors, including IL-1 and IL-6, which aggravate vascular damage and endothelial dysfunction, ultimately leading to HTN39." (PMID 40097561, 2025). "We found that blood samples of individuals living with obesity or palmitate priming enhanced the acetylation of H3K18 and is associated with increased gene expression of this IL‐6 and pro‐IL‐1β." (PMID 40265287, 2025).